ESR1 (estrogen receptor 1)
Diseases named in the same sentence as ESR1 in open-access papers (continued):
Sharing a sentence is not in itself a finding about the gene and the disease.
tumor (4,306 papers, 1999 to 2026). "Collectively, our findings reveal that ESR1 mutations contribute to an immunosuppressive tumor microenvironment by dampening cytokine secretion and immune cell activity." (PMID 41797713, 2026). "Some reports even correlate ESR1 mutations with changes in the tumor microenvironment, such as increased angiogenesis, altered cell adhesion, and changes in immune evasion mechanisms, all leading to metastatic proliferation." (PMID 40731911, 2025). "Decisions should integrate patient preferences, tumor characteristics, prior therapy, and actionable biomarkers such as ESR1 and PIK3CA mutations, AKT pathway alterations, HER2-low/ultra-low status, and germline BRCA mutations." (PMID 41226406, 2025). "In vivo, imlunestrant outperformed fulvestrant, leading to tumor regression in a patient-derived xenograft harboring the Y537S ESR1 mutation." (PMID 40327396, 2025). "Giredestrant (GDC-9545) is a SERD, active either as monotherapy or in association with a CDK4/6i in ESR1 mutant or wild-type tumor models." (PMID 40244377, 2025). "The PADA-1 trial provided compelling evidence supporting a molecularly guided approach by demonstrating that early intervention based on the detection of rising ESR1 mutations in circulating tumor DNA (bESR1mut) significantly prolonged PFS." (PMID 40989687, 2025). "Decreasing mutant PIK3CA circulating tumor DNA (ctDNA) during treatment and estrogen receptor 1 (ESR1) mutations at baseline were related to a better prognosis, making them candidate biomarkers." (PMID 39717717, 2025). "Circulating tumour DNA ESR1 mutations (ctESR1m) were the most prevalent, present in 16 patients (76%) with both stable (SD) and progressive disease (PD), showing no clear association with disease progression." (PMID 41364261, 2025). "This emphasizes the need for the longitudinal monitoring of ESR1 mutations in patients undergoing ET, using methods that can capture tumor heterogeneity." (PMID 40282442, 2025). "Approximately half of all patients with evaluable circulating tumor DNA (ctDNA) at baseline had ESR1 mutations (51/96 [53.1%])." (PMID 40598566, 2025). "Amcenestrant also demonstrated potency in tumours harbouring an ESR1 mutation that confers resistance to fulvestrant." (PMID 39859174, 2025). "Recently, it has been established that estrogen receptor (ER) alpha (ESR1) activating mutations play a pivotal role in driving tumor progression in (HR)+/HER2- BC patients after first line of endocrine therapy (ET)." (PMID 40792231, 2025). "The detection of ESR1 mutations in ctDNA through liquid biopsy allows the molecular evaluation of the tumor using a minimally invasive alternative to solid tissue-based genotyping [6,8,19,]." (PMID 41142848, 2025). "While an exploratory analysis of circulating tumor DNA suggested that the presence of an ESR1 or PIK3CA mutation negated any benefit from adding ribociclib, these were small and post hoc analyses." (PMID 41226406, 2025). "In the first‐in‐human clinical trial of the KAT6 inhibitor PF‐07248144, researchers performed preliminary biomarker analyses of circulating tumor DNA (ctDNA) mutation profiling at baseline, including ESR1 and PIK3CA/PTEN/AKT1 genes." (PMID 41357671, 2025). "The importance of analyzing and monitoring ctDNA was demonstrated within the PAlbociclib and Circulating Tumor DNA for ESR1 Mutation Detection (PADA-1) trial." (PMID 39839709, 2025). "Exploratory analysis from the MAINTAIN trial suggested that the presence of ESR1 mutation in circulating tumor DNA is detrimental to ‘maintaining’ CDK4/6i treatment." (PMID 40427107, 2025).
tumor (continued). "Tracking ESR1 mutations through plasma‐cfDNA analysis is highly beneficial for the identification of tumor molecular dynamics and the improvement of personalized treatments for MBC patients as this is highlighted by several studies." (PMID 39754401, 2025). "Plasma cell‐free DNA (cfDNA) analysis to track estrogen receptor 1 (ESR1) mutations is highly beneficial for the identification of tumor molecular dynamics and the improvement of personalized treatments for patients with metastatic breast cancer (MBC)." (PMID 39754401, 2025). "To strengthen the association between ESR1 mutations and liver metastasis, we analyzed 1918 tumor samples from a publicly available primary and metastatic breast cancer dataset." (PMID 39470848, 2025). "We explored the impact and potential underlying mechanisms of ESR1 on the malignant behaviour of tumour stem cells under oestrogen stimulation and provided insights for clinical treatment." (PMID 40342082, 2025). "Higher mRNA expression of ESR1 gene was associated with increased tumor size (p = 0.002), more involved lymph nodes (p = 0.03), and higher stage (p = 0.002)." (PMID 40666735, 2025). "ESR1 mutations can affect the proliferation and metastasis of tumor cells by modulating the interaction between ERα protein and other signaling pathways, including the PI3K/AKT and MAPK signaling pathways." (PMID 41357671, 2025). "Variants in the ESR1 gene can lead to endocrine therapy resistance and poorer survival, thus having predictive significance in influencing treatment efficacy and tumor progression." (PMID 40941673, 2025). "•Using plasma-cfDNA analysis to track ESR1 mutations is highly beneficial for identifying tumor molecular dynamics and improving personalized treatments for mBC patients." (PMID 40027941, 2024). "This study aimed to investigate the prognostic value of c-MET-positive circulating tumor cells (cMET+ CTCs), ESR1/PIK3CA mutations, and cell-free DNA (cfDNA) concentrations in patients with hormone receptor-positive (HR+) metastatic breast cancer (mBC)." (PMID 38238761, 2024). "ESR1 mutational status was determined by analyzing blood circulating tumor deoxyribonucleic acid (ctDNA) using the Guardant360 CDx assay." (PMID 38800404, 2024). "The result demonstrates a high concordance rate between the tumor tissue and ctDNA (91%), indicating the reliability and feasibility of liquid biopsy for the ESR1 variant detection." (PMID 39201281, 2024). "ESR1 mutations are prevalent in advanced and metastatic breast cancer, prompting the exploration of targeted therapeutics tailored to ESR1‐mutant tumours." (PMID 39417215, 2024). "The miR-18a/low tumours had higher expression of the luminality-associated genes like ESR1, GATA3, FOXA1, XBP1 and TFF1 and a lower expression of the basality-associated genes such as KRT18, KRT17, FOXC1, ANLN, STIL and MIA (p < 0.05)." (PMID 38786043, 2024). "Among patients with ESR1 mutation, lasofoxifene has been shown to inhibit tumor growth compared to fulvestrant." (PMID 39063972, 2024). "For example, EGFR plays an important role in the growth and reproduction of tumor cells, and ESR1 can cause abnormalities in the estrogen signaling pathway, thereby affecting the growth and metastasis of tumor cells." (PMID 39457402, 2024). "We found that under hypoxic tumor conditions, 2 distinct tumor immuno-angiogenic ecosystems develop linked to sex differences and ESR1 expression is generated." (PMID 38411438, 2024). "Conversely, expression of ESR1 in non-tumor tissues was associated with more favorable prognostic indicators, a trend which was further accentuated following treatment with the NC2603 analog." (PMID 38732206, 2024). "It is now clear that plasma-cfDNA analysis to track ESR1 mutations is highly beneficial for identifying tumor molecular dynamics and improving personalized treatments for mBC patients." (PMID 40027941, 2024).
tumor (continued). "PlasmaMATCH Cohort A (NCT03182634) investigated the activity of fulvestrant in patients with activating ESR1 mutations in circulating tumor DNA (ctDNA)." (PMID 37982575, 2024). "We utilized the targeted sequencing of hotspot mutations of the helix 12 of the ESR1 gene in formalin-fixed paraffin-embedded tumor samples." (PMID 39272884, 2024). "The data from the FERGI, SoFEA, EFECT, and PALOMA-3 trials were analyzed retrospectively to evaluate the impact of a mutation in ESR1 on the tumor response to fulvestrant." (PMID 38930141, 2024). "Of note, ESR1 has been found to encode gain-of-function mutations that promote tumor metastasis and resistance to endocrine therapy and can be detected with a liquid biopsy." (PMID 39057065, 2024). "In preclinical trials, Vepdegestrant exhibited promising results with tumor regression in PDX models with ESR1 mutations." (PMID 38339303, 2024). "The researchers compared ctDNA with matched tumor tissue data and found that ESR1 mutations (0/81), (3/31), and (12/19) were present in tumor tissues collected at the initial diagnosis, before AI treatment, and after AI treatment progression, respectively." (PMID 39544302, 2024). "Silencing genes that encode hormone receptors, like ESR1 for ERα, can affect tumour response to estrogen." (PMID 39846533, 2024). "Of the 35 patients, 22 (62.9%) had one or more detectable ESR1 mutations in circulating tumor (ct)DNA at baseline." (PMID 38824244, 2024). "Among patients with HER2-low tumor expression and ESR1-mutated tumors, the mPFS with elacestrant was 9.0 versus 1.9 months with SOC (HR, 0.30; 95% CI, 0.14–0.60)." (PMID 39087959, 2024). "In contrast, the expression of target ESR1 mRNA was significantly downregulated along with the increase in tumor grade, and was associated with the progressive loss of ERα immunoexpression." (PMID 36978627, 2023). "Mutations and overexpression of ESR1 have been detected in tumor samples, suggesting potential drug target against human cancers." (PMID 37155147, 2023). "Low or undetectable in all the sampled tumor tissues, ESR1 mutations expanded rapidly in blood during HER2/hormone double-blockade, and predicted life-threatening local progression at lung and liver metastatic foci." (PMID 36713585, 2023). "We focused on two mutations with a higher frequency of ESR1 mutations to extract and analyze the maximum amount of mRNA from a limited amount of tumor tissue because ddPCR requires analysis for each position of the mutation." (PMID 37174098, 2023). "A conventional tumor tissue biopsy can be used to detect ESR1 mutations; however, these mutations are less likely to present on initial tissue biopsy, and such an invasive approach is hardly repeatable over time for longitudinal disease monitoring." (PMID 37958343, 2023). "Detection of ESR1 mutations in CTCs and ctDNA is clinically important in comparison to primary tumours since the analysis of serial biopsies of metastatic lesions is difficult and highly invasive." (PMID 37046848, 2023). "A unique observation of our study is the substantial overlap of genes involved in tumor manifestation/association with the genes involved in cardiotoxicity and neurotoxicity such as ESR1, PTGS2, LTA and KDR." (PMID 37069190, 2023). "A third patient had detectable PIK3CA and ESR1 mutations at baseline that became undetectable in all subsequent visits during the 36 months of treatment, and sustained tumor-size reduction was observed throughout treatment." (PMID 37580773, 2023). "Rintodestrant is a novel orally bioavailable SERD that has demonstrated potent tumor inhibition in animal models with tamoxifen resistance and ESR1 mutations." (PMID 37019913, 2023).
tumor (continued). "It is known that patients with advanced BC have undergone prior aromatase inhibitor therapy followed by a selection of ESR1 mutations by the time of tumor progression; therefore, attempts are being made to find new effective combinations for their treatment." (PMID 38069396, 2023). "While most excess PIK3CA mutations were detected in tissue, discordant ESR1 mutations were balanced between tumor and plasma." (PMID 37511178, 2023). "For example, the sensitivity of a tumor to therapy changes due to the loss of receptors in metastatic and recurrent foci, as well as the acquisition of mutations (for example, ESR1 during hormone therapy with aromatase inhibitors)." (PMID 38069396, 2023). "Consistent with the subtype association, tumor DNAm AA was positively correlated with ESR1 (Pearson r = 0.39, P = 6.3e−06) and PGR (Pearson r = 0.36, P = 2.4e−05) gene expression." (PMID 36991516, 2023). "Circulating tumor DNA (ctDNA) is now often used as a non-invasive tool for the identification of ESR1 mutations." (PMID 37226020, 2023). "Liquid biopsy is a valid, inexpensive, and attractive noninvasive alternative to tumor biopsies for the identification of ESR1 mutations." (PMID 37675216, 2023). "Blood-based ESR1 mutation detection is preferred over tumor tissue testing due to the higher sensitivity." (PMID 38001722, 2023). "In conclusion, the present pooled meta-analysis only provides additional evidence that liquid biopsies can replace tumor tissue biopsies in molecular screening programs for ESR1 mutations in a potentially easier and cost-effective approach." (PMID 37675216, 2023). "The PADA-1 trial showed that the combination of fulvestrant with palbociclib prolonged PFS in patients with rising ESR1 mutations detected by circulating tumor (ct)DNA." (PMID 37000345, 2023). "INTEGRATE detected several ESR1 gene fusions in our tumor cohort, which have previously been implicated in breast and ovarian cancer." (PMID 37400526, 2023). "ESR1 mutations are a new prognostic factor for low survival, their occurrence can be monitored in circulating tumor DNA (ctDNA) by digital PCR (dPCR)." (PMID 37924026, 2023). "Preclinical studies showed that lasofoxifene, a potent antagonist of both wild-type and mutant ER28, was effective in reducing tumor growth in an endocrine-resistant ESR1-mutated xenograft model." (PMID 37684290, 2023). "Elevated expression of genes connected with metastasis, in cells expressing the Y537S and D538G mutations and increased metastatic potential in tumour xenografts, also implicates ESR1 mutations in driving transcriptomic reprogramming that promotes metastasis." (PMID 36198774, 2022). "OTX015 inhibits tumor growth in cell line- and patient-derived xenografts harboring ESR1 Y537S mutation." (PMID 35881485, 2022). "Several studies have focused on establishing new therapeutic strategies for tumor tissues with ESR1 mutations in recent years." (PMID 36212140, 2022). "In the present study, we report that, using drop-off ddPCR, ESR1 mutations were detected in 15% of primary tumor tissues and in 13.8% of plasma-cfDNA samples tested." (PMID 35954453, 2022). "Mechanistically, AD suppressed estrogen receptor 1 (ESR1, encodes ER-α) transcription to inhibit tumor growth." (PMID 35615146, 2022). "Noteworthy, within the Luminal A tumours a group of patients showed lower levels of ESR1 were associated with higher levels of ERBB2 signaling, especially when compared with other subtypes." (PMID 35985932, 2022). "Analysis of plasma circulating tumor DNA to detect ESR1 point mutations by droplet digital PCR (ddPCR) is now done in the clinic and clinical trials are investigating the use of these assays in real-time." (PMID 36686845, 2022).
tumor (continued). "ESR1 was identified as a tumour suppressor gene in HCC and its genetic polymorphism was significantly associated with susceptibility to HCC in Chinese hepatitis B virus carriers." (PMID 35141281, 2022). "Elacestrant is currently under investigation in phase III clinical trial (EMERALD) (NCT03778931) in patients with ER+/HER2-negative advanced BC17, including patients whose tumours harbour ESR1 mutations." (PMID 36446866, 2022). "The reduced ESR1 expression is associated with a high liver injury score, tumor size, and pathological invasion of the intrahepatic portal vein." (PMID 35872841, 2022). "ESR1 mutations are detected in less than 1% of original tumours, however they are reported in 20–40% of tumours after endocrine therapy and have been associated to poor AI & tamoxifen efficacy." (PMID 36212140, 2022). "Specifically, we analyzed on formalin-fixed paraffin-embedded tumor samples ESR1 and PI3KCA mutations and miRNAs profiles." (PMID 35896637, 2022). "These ESR1 wild‐type cells are likely remnants of a more primordial tumor state before acquisition of ESR1 mutation due to AI selective pressure at some point during the patient’s cancer history." (PMID 34866317, 2022). "A study done by Caliguiri and colleagues show that pRb loss in tumor cells attenuates the expression of ESR1 protein by the activation of the proteasome pathway." (PMID 35359459, 2022). "Work published shortly thereafter on patient-derived circulating tumor cell (CTC) lines confirmed that primary cancer cells with ESR1 mutations are relatively resistant to endocrine therapy and sensitive to ESR1 depletion." (PMID 34392831, 2021). "DNA extracted from formalin fixed paraffin embedded (FFPE) tumor specimens and ctDNA from matched plasma were analyzed by droplet digital (dd)PCR for the main ESR1 mutations (Y537S, Y537C, Y537N, D538G, E380Q)." (PMID 33777770, 2021). "CircGRB10 and circTTC28 interacted with miR-18a-5p and miR-20b-5p, respectively, to regulate the expression of gene ESR1, which was detected as a candidate tumor suppressor gene and reported to be associated with the susceptibility to persistent HBV infection." (PMID 34201256, 2021). "Recent, retrospective analyses of ESR1 mutations in circulating tumour DNA suggested that the occurrence of the mutations was associated with poor overall survival and resistance to hormonal treatment in patients with metastatic disease." (PMID 34930150, 2021). "Its expression has been shown to inversely correlate with HCC tumor size and disease stage in a genome-wide expression analysis, consistent with preclinical data demonstrating that loss of ESR1 accelerates carcinogenesis." (PMID 34881186, 2021). "The majority of resistant tumours remain dependent on ERα-action, with activating ESR1 gene mutations occurring in 15–40% of advanced cancers." (PMID 34944934, 2021). "We present here the development and analytical validation of a highly sensitive and specific NAPA assay for the detection of four ESR1 mutations (Y537S, Y537C, Y537N and D538G) in the primary tumours, CTCs, and plasma-ctDNA of ER+ BrCa patients." (PMID 33535614, 2021). "For the reasons stated, we reported an association between the methylation at 151-bp island of the ESR1 gene and immunohistochemical tumor characterization." (PMID 34863151, 2021). "ESR1 SNPs are associated with tumour carcinogenesis, cell proliferation, metastasis, and prognostic." (PMID 34930150, 2021). "ESR1, an estrogen receptor, has been identified as a potential marker for identifying individuals at increased risk of neoplasia among those with long-standing and extensive UC." (PMID 34177580, 2021).